PDE4D (phosphodiesterase 4D)
Diseases named in the same sentence as PDE4D in open-access papers (continued):
Sharing a sentence is not in itself a finding about the gene and the disease.
lung carcinoma (14 papers, 2011 to 2025). "PDE4D is overexpressed in LKB1-mutated lung cancer; therefore, PDE4 inhibitors may be more effective in treating LKB1-mutated lung cancer." (PMID 38233872, 2024). "The high expression of PDE4D has been reported to be associated with aggressive disease in multiple cancers, with therapeutic potential reported for pancreatic ductal adenocarcinoma, tamoxifen-resistant ER-positive breast cancer, lung cancer and colon cancer." (PMID 36045381, 2022). "PDE4D is highly expressed in a variety of cancer types, including pancreatic cancer, lung cancer, breast cancer, and prostate cancer." (PMID 37427586, 2023). "In recent years, PDE4 subtype, PDE4D, has been identified as a cancer-promoting molecular that represents a novel target in many types of cancer including as lung cancer, melanoma, colorectal cancer, leukemia, colon cancer and glioma." (PMID 34066000, 2021). "PDE4D (Ser14Phefs*11), which was mutated in ALK16, was shown to impair cAMP generation through cAMP hydrolysis in lung cancer cell lines." (PMID 29300322, 2018). "A study revealed that hypoxia via hypoxia-inducible factor 1α regulates PDE4D in lung cancer cell lines, including H1975, and treatment with the first-generation PDE4D inhibitor rolipram decreased cell proliferation." (PMID 26639561, 2015). "Furthermore, PDE4D has been suggested as a potential therapeutic target in lung cancer as its silencing affects both proliferation and metastasis in tumor cells." (PMID 40430005, 2025). "PDE4A and PDE4D promote HIF signaling in lung cancer through cAMP-PKA/EPAC pathways." (PMID 38233872, 2024). "PDE4D may support proliferation in prostate and lung cancer, and cAMP is able to augment or suppress ERK activity in a cell type-dependent manner." (PMID 34271981, 2021). "In addition, phosphodiesterase 4D (PDE4D) stimulates the development of lung cancer through TGF-β1." (PMID 36278172, 2022). "Moreover, PDE4D inhibitors (rolipram, roflumilast, and GEBR-7b) have been extensively studied for preventing inflammatory diseases and cancer cell tumor growth specifically in lung cancer and breast cancer." (PMID 37427586, 2023). "These individual CRTC knockout cells showed a reduction in expression of several CREB-mediated target genes, such as PDE4D, INSL4, LINC00473, and NR4A2, but not to the extent of their endogenous levels in LKB1-wt lung cancer H522 cells, as assayed by western blotting or RT-qPCR assays." (PMID 34142658, 2021).
breast cancer (13 papers, 2016 to 2025). A primary or metastatic malignant neoplasm involving the breast. "Analysis of a large dataset comprising 2283 patients with primary, ER+ breast cancer treated with endocrine therapy revealed that high mRNA expression of PDE4D is associated with significantly worse relapse-free survival (RFS) also in early-stage disease." (PMID 37914699, 2023). "In breast cancer patients treated with tamoxifen, PDE4D overexpression is associated with worse survival." (PMID 35615145, 2022). "In breast cancer, resistance to tamoxifen can be caused by overexpression of phosphodiesterase 4D (PDE4D)." (PMID 32046099, 2020). "We observed a positive correlation between LINC00152 and PDE4D mRNA in ER+ breast cancer patients progressed upon tamoxifen therapy in GSE6532 dataset, suggesting mRNA level regulation of PDE4D by LINC00152." (PMID 38879508, 2024). "PDE4D also showed a positive correlation with LINC00152 at the protein level in our own cohort of ER+ breast cancer patients." (PMID 38879508, 2024). "Supporting these, overexpression of PDE4D in ER+ breast cancer cells almost completely blocked SOC-induced mitochondrial ROS generation and rescued G1/S progression and cell viability by preventing DNA damage and BRCAness in the BRCA1/2 wt cells." (PMID 37914699, 2023). "GSEA analysis in an ER+/HER2- breast cancer dataset revealed significant enrichment of genes upregulated upon EGFR overexpression among high PDE4D-expressing patients’ tumors." (PMID 37914699, 2023). "We observed a sharp decrease in the levels of PDE4D upon treatment of ER+ breast cancer cells with SOC that accompanies increased PKA phosphorylation and reduced RB phosphorylation." (PMID 37914699, 2023). "Gene Set Enrichment Analysis (GSEA) in an ER+/HER2- breast cancer dataset revealed significant enrichment of genes upregulated in ER+ as compared to ER- tumors among high PDE4D-expressing patients’ tumors." (PMID 37914699, 2023). "Next, we analyzed the effects of PDE4D protein levels on patient survival and disease relapse in our own cohort of 171 early and late-stage ER+ breast cancer patients treated with endocrine therapy." (PMID 37914699, 2023). "After screening, source genes closely associated with canine mammary tumours were found to include RYR2, PDE4D, ROCK2, CREB3L2 and UBA3, and associated circRNAs included chr27:26618544-26687235-, chr26:8194880-8201833+ and chr17:7960861-7967766-." (PMID 35622733, 2022). "Known for its role in anchoring phosphodiesterase 4D to the Golgi/centrosome region of the cell, deleterious mutations of PDE4DIP have recently been demonstrated to be involved in breast cancer." (PMID 27829003, 2016). "Moreover, an elevation in PDE4D expression has been observed in tamoxifen-resistant cells and breast cancer tissues." (PMID 40129976, 2025). "In addition, small molecules able to block PDE4D isoforms have been recently studied for the treatment of specific cancer types, particularly hepatocellular carcinoma and breast cancer." (PMID 39125619, 2024). "Importantly, high LINC00152 expression is significantly correlated with high PDE4D/low ferroptosis and worse survival in multiple cohorts of tamoxifen- or tamoxifen-containing endocrine therapy-treated ER+ breast cancer patients." (PMID 38879508, 2024). "Possibly even more significantly, precise inhibition of PDE4D, whether through genetic approaches or by employing the PDE4D inhibitor Gebr-7b, re-established chemosensitivity in estrogen receptor-positive breast cancer cells that had become resistant to chemotherapy." (PMID 40129976, 2025). "We demonstrated the clinical relevance of the LINC00152/PDE4D/cAMP/Ca2+/ferroptosis axis and showed that higher LINC00152 levels are associated with worse survival in multiple cohorts of endocrine therapy-treated ER+ breast cancer patients as well as other cancers." (PMID 38879508, 2024).
breast cancer (continued). "At the same time, the PDE4D isoform has been investigated for its role in cancer development, particularly in hepatocellular carcinoma (HCC), breast cancer, and acquired tamoxifen-resistant breast cancer." (PMID 39125619, 2024). "We stimulated ER+ breast cancer cells with EGF and observed a significant increase in PDE4D levels at both mRNA and protein levels." (PMID 37914699, 2023). "To test the clinical relevance of PDE4D in SOC resistance, we re-analyzed a metastatic, endocrine therapy-treated ER+ breast cancer patient dataset, GSE12464728." (PMID 37914699, 2023). "We also found EGFR, MYCN, and MYC in brain cancers;39,40BCL2, MYC, and the loci of IGH translocations in lymph-nodes cancer;41–43CDK12 in breast cancer; CCND1 in liver cancer; and RUNX1, GATA6, and PDE4D in esophageal cancer." (PMID 36163358, 2022). "In addition, very recently, small molecules able to block the PDE4D isoform have been studied for the treatment of specific tumors, particularly in HCC and breast cancer." (PMID 39125619, 2024). "In addition, PDE4D is known to inhibit cAMP/ER stress/p38-JNK signaling and apoptosis in tamoxifen-resistant ER-positive Breast Cancer cells." (PMID 35615145, 2022).
colorectal cancer (13 papers, 2019 to 2025). A primary or metastatic malignant neoplasm that affects the colon or rectum. "Our previous study found that down-regulation of PDE4D caused BIM-mediated cell growth arrest in colorectal cancer cells." (PMID 31772658, 2019). "Recent studies have shown that PDE4D is a key metastasis-driving target for promoting metachronous metastasis of colorectal cancer through the HIF-1α-CCN2 pathway." (PMID 40564004, 2025). "Recent studies have demonstrated that inhibition of PDE4D with rolipram or roflumilast can decrease the malignant properties of colorectal cancer cells by repressing the AKT/mTOR/Myc signaling pathway, which is vital for tumor growth and survival." (PMID 40564004, 2025). "PDE4D overexpression induces colony formation, cell proliferation, and anchorage−independent growth in colorectal cancer cells." (PMID 35615145, 2022). "Consistently, mir-224-5p and mir-203a have been reported to be correlated with poor OS of CRC patients and promote colorectal cancer proliferation and migration by targeting PDE4D, respectively." (PMID 32802869, 2020). "MiR203a-3p was found to be up-regulated also in colorectal cancer, where it promotes proliferation, invasion and migration by suppressing expression of PDE4D." (PMID 31775395, 2019). "We speculated that PDE4D plays a key role in the pathogenesis of colorectal cancer liver metastasis." (PMID 39956959, 2025). "More recently, PDE4D has been identified as a novel tumor-promoting molecular which represents a unique targetable enzyme in various human cancers, such as lung, prostate, melanoma, ovarian, endometrial, colorectal cancer and gastric cancers 14-17." (PMID 31772658, 2019). "In addition, PDE4D has been found to serve as an oncogene regulated by miRNAs to promote tumor progression in various human cancers, such as miR-494-PDE4D in gastric cancer and miR-203a-3p-PDE4D and miR-139-5p-PDE4D in colorectal cancer." (PMID 33519668, 2020). "To confirm that PDE4D promotes colorectal cancer metastasis by upregulating CCN2, we performed immunofluorescence (IF) in PDE4D inhibitor (roflumilast) treated MC38 cells." (PMID 39956959, 2025). "The newly synthesized compound L11 can specifically inhibit PDE4D and eliminate metachronous metastasis of colorectal cancer without obvious toxic and side effects." (PMID 40564004, 2025). "We further found cAMP‐specific 3′,5′‐cyclic phosphodiesterase 4D (PDE4D) as an essential therapeutic target for liver metastases of CRC and interfering the function of PDE4D could repress colorectal cancer metastases." (PMID 39956959, 2025).
Cognitive impairment (9 papers, 2019 to 2024). Abnormal cognition is characterized by deficits in thinking, reasoning, or remembering. "Indeed, the pharmacological inhibition of two PDEs (PDE2A and PDE4D) has been associated with multiple autism-like behaviors and cognitive deficit at different ages in mouse models." (PMID 33414502, 2021). "PDE4D variants might be a main reasons underlyling for the abnormal topological properties and cognitive impairment." (PMID 32849849, 2020). "Thus, our findings indicated that the disruption of the LTP effect and/or the inflammatory effect caused by the PDE4D variants might be the main reason for the abnormal topological properties and cognitive impairment." (PMID 32849849, 2020). "Although the underlying mechanisms of the cognition-enhancing effect remain elusive, PDE4D inhibition appears to be an interesting novel therapeutic option for cognitive deficits, particularly in AD." (PMID 39125619, 2024). "The high expression levels of PDE4D isoforms in the CNS support medicinal chemistry studies for the identification of selective PDE4Dis, useful for the treatment of different cognitive disorders." (PMID 39125619, 2024). "Relatively low doses of BPN14770 were effective at reversing scopolamine-induced memory and cognitive deficits in humanized PDE4D mice." (PMID 33363155, 2020). "The recent large scale GWAS studies of human cognitive ability suggest the potential of PDE1C, PDE4B and PDE4D inhibitors to address cognitive impairment across multiple CNS disorders." (PMID 30800055, 2019). "The present study determined whether and how PDE4D knockdown by microinjection of lenti-PDE4D-miRNA into the prefrontal cortex reversed Aβ1–42-induced cognitive impairment in behavioral, neurochemical, and molecular biology assays." (PMID 34539384, 2021). "Additionally, the brain network mechanism of the cognitive impairment due to PDE4D, and the enhancement of PDE4D inhibitors need further study." (PMID 32849849, 2020). "Given the interest in PDE4D as a therapeutic target for cognitive disorders, better understanding of its precise anatomical localization in primate dlPFC should help to guide more informed strategies for treating higher cognitive deficits." (PMID 33328902, 2020). "Thus, a combined therapy aimed at inhibiting PDE5 and PDE4 enzymes (especially some isoforms, such as PDE4D) could be more effective in ameliorating cognitive deficits in AD patients, as already shown in aged rodents." (PMID 33451088, 2021). "More recent work found that the subtype selective, PDE4D allosteric inhibitor, BPN14770 was able to improve memory and cognitive deficits in a mouse model of AD." (PMID 33363155, 2020). "In conclusion, the results of our study demonstrate that subacute treatment with PDE4D inhibitor BPN14770 is effective at alleviating scopolamine-induced memory and cognitive impairment." (PMID 33363155, 2020).
heart failure (9 papers, 2010 to 2025). Inability of the heart to pump blood at an adequate rate to meet tissue metabolic requirements. "A study using PDE4D KO mice, clearly demonstrated that PDE4D deficiencies in the ryanodine receptor (RyR) complex promote heart failure and arrhythmias." (PMID 36142518, 2022). "Similar to PDE3A, another isoform, PDE4D, appears to be cardioprotective as mice deficient in PDE4D developed cardiac dysfunction and accelerated heart failure following MI." (PMID 28101515, 2016). "PDE4D deficiency in the ryanodine-receptor complex (RyR2) in mice was also involved in heart failure." (PMID 21151982, 2010). "Furthermore, it was reported that the deletion of PDE4D leads to an increase in RyR2 phosphorylation and an elevated risk of arrhythmias, thereby further accelerating the progression of heart failure." (PMID 40136709, 2025). "Indeed, PDE4D knockout mice presents a progressive cardiomyopathy with a loss of β-adrenergic signaling in cardiac myocytes and heart failure after myocardial infarction." (PMID 33807511, 2021). "Furthermore, inactivation of the PDE4D gene in mouse was associated with progressive heart failure and arrhythmias, despite a normal overall cAMP level." (PMID 21151982, 2010). "Meanwhile, previous reports show that PDE4D3 also binds to RyR2, and global deletion of PDE4D leads to calcium leakage through RyR2 and heart failure in ageing mice." (PMID 39662482, 2025). "This review highlights the cardiac PDE4 isoforms PDE4A, PDE4B and PDE4D, focusing on their distinct localisation and contributions to cardiac physiology and pathophysiology, particularly in heart failure and arrhythmias." (PMID 40136709, 2025). "Therefore, PDE4D is a potential therapeutic target for heart failure treatment, but its intervention strategies require optimization based on precise regulation of cAMP signaling." (PMID 40015131, 2025). "Cardiac PDE4B overexpression is beneficial in remodeling and heart failure (HF), however, the effect of PDE4D and PDE4 inhibitor in HF remains unclear." (PMID 40015131, 2025). "Altogether, decreases in PDE4D activity, which represents the main PDE4 isoform in human cardiac tissue, might favor idiopathic dilated cardiomyopathy and its deficiency in the RyR complex promotes heart failure and arrhythmias, whereas PDE4B prevents Ca2+ overload and arrhythmias." (PMID 36142518, 2022). "It is already known that HSP20 exists in a complex with AKAP‐Lbc 24 and PDE4D 11, and that dissociation of PDE4 from this signalosome results in the phosphorylation of HSP20, which acts to attenuate hypertrophic signalling in a heart failure model." (PMID 28097089, 2017).
Intellectual disability (9 papers, 2017 to 2025). "This specific PDE4D plays a crucial role in modulating cAMP levels relevant to human cognition, as ultra-rare autosomal dominant mutations in PDE4D have been linked to a neurodevelopmental syndrome with intellectual disability." (PMID 40299377, 2025).
melanoma (8 papers, 2014 to 2025). A malignant, usually aggressive tumor composed of atypical, neoplastic melanocytes. "Overall, 3.5% of solid tumors (including melanoma) have homozygous microdeletions of PDE4D associated with increased expression and a tumor-promoting effect." (PMID 35158973, 2022). "PDE4D expression is elevated in advanced melanoma and negatively associated with survival." (PMID 35158973, 2022). "Higher PDE4D levels has also been shown to be correlated with worse survival in solid tumors, such as lung, prostate, melanoma, ovarian, endometrial, colorectal and gastric cancers." (PMID 37914699, 2023). "High expression of PDE4D (subtype PDE4D2) significantly enhanced the proliferation of A375 melanoma cells and HGC-27 gastric cancer cells both in vitro and in vivo." (PMID 31772658, 2019). "Our results showed that THOC2 inhibition significantly reduced the expression of PDE4D, PIK3CA, GNAI1, ADCY1, HHIP and ADORA2A in melanoma cells." (PMID 31680623, 2019). "THOC2 expression was positively correlated with PDE4D, PIK3CA, GNAI1, and HHIP expression in melanoma tissues." (PMID 31680623, 2019). "Silencing PDE4B or PDE4D significantly reduced PDE4 activity in melanoma cells, whereas PDE4A had no such effect, suggesting that PDE4B and PDE4D play crucial roles in regulating PDE4 activity in melanoma." (PMID 40129976, 2025). "In addition, correlation analysis showed that THOC2 expression was correlated with PDE4D, PIK3CA, GNAI1, and HHIP expression in melanoma tissues." (PMID 31680623, 2019).
myocardial infarction (8 papers, 2009 to 2025). Gross necrosis of the myocardium, as a result of interruption of the blood supply to the area, as in coronary thrombosis. "It was reported that PDE4D homozygous null mice showed progressive cardiomyopathy and accelerated HF after myocardial infarction, which is likely due to the reduced PDE4D3 activity in ryanodine receptor signaling complex causes defective ryanodine receptor-channel function." (PMID 40015131, 2025). "This may explain why the findings of our study of heterozygous PDE4D knockout mice were inconsistent with those of the literature that complete knockout of PDE4D fosters HF development following myocardial infarction." (PMID 40015131, 2025). "Accordingly, XIST may suppress the proliferation of post-myocardial infarction cells and promote apoptosis by targeting miR-130a-3p and PDE4D in a straight line." (PMID 31942979, 2020). "Interestingly, Pde4d gene knockout in mice resulted in a spontaneous DCM phenotype, as well as worse outcome after myocardial infarction." (PMID 38572067, 2024). "lncRNA Xist, which positively mediates PDE4D expression via interacting miR-130a-3p and targets miR-101a-3p through regulating FOS, promotes myocardial infarction development and cell apoptosis, and inhibits cell proliferation though the miR-130a-3p/PDE4D aixs and miR-101a-3p/FOS aixs." (PMID 34178980, 2021). "In post-myocardial infarction cells, it has been confirmed that X-inactive specific transcript RNA (XIST) can negatively mediate miR-130a-3p expression, and miR-130a-3p represses expression of PDE4D." (PMID 31942979, 2020). "However, few studies have analyzed the relationship between phosphodiesterase 4D (PDE4D) and myocardial infarction (MI)." (PMID 30713479, 2018).